COLGALT2 (collagen beta(1-O)galactosyltransferase 2)
Description:
Beta-galactosyltransferase that transfers beta-galactose to hydroxylysine residues of collagen.
Synonyms: ColGalT 2; C1orf17; GLT25D2; KIAA0584
Tractability: Antibody: UniProt predicts a signal peptide or a membrane-spanning region.
Gene: Protein-coding gene on chromosome 1 (183,929,854 to 184,037,729, reverse strand). Ensembl gene ENSG00000198756.
Subcellular location: Endoplasmic reticulum lumen
Subcellular location (Human Protein Atlas): Nucleoplasm; Vesicles
Pathways (Reactome):
Extracellular matrix organization: Collagen biosynthesis and modifying enzymes
Gene Ontology:
Molecular function: protein binding; procollagen galactosyltransferase activity
Biological process: collagen fibril organization
Cellular component: endoplasmic reticulum lumen
Genetic constraint (gnomAD): Loss-of-function variants: 35 observed, 58.01 expected, observed/expected ratio (o/e) 0.6, 90% interval 0.46 to 0.8. The upper end of that interval is the gene's LOEUF score, 0.8, which puts it in group 3 of 6, group 1 being the genes least tolerant of losing a copy. Missense variants: 646 observed, 693.94 expected, observed/expected ratio (o/e) 0.93, 90% interval 0.87 to 0.99. Synonymous variants: 277 observed, 278.88 expected, observed/expected ratio (o/e) 0.99, 90% interval 0.9 to 1.1.
Homologues: Orthologues: chimpanzee COLGALT2 (99% identical), macaque COLGALT2 (98% identical), guinea pig COLGALT2 (94% identical), rat Colgalt2 (94% identical), pig COLGALT2 (94% identical), dog COLGALT2 (93% identical), mouse Colgalt2 (92% identical), tropical clawed frog colgalt2 (74% identical), zebrafish colgalt2b (61% identical), zebrafish colgalt2a (55% identical), Drosophila melanogaster CG31915 (42% identical), Caenorhabditis elegans D2045.9 (30% identical). Paralogues in human: COLGALT1 (64% identical), CERCAM (50% identical), PLOD3 (22% identical), PLOD2 (21% identical), PLOD1 (20% identical).
Diseases named in the same sentence as COLGALT2 in open-access papers:
COLGALT2 is named in the same sentence as 18 diseases in open-access papers, as found by Europe PMC text mining. Sharing a sentence is not in itself a finding about the gene and the disease. The quoted sentences say what the papers report.
osteosarcoma (8 papers, 2020 to 2023). A usually aggressive malignant bone-forming mesenchymal neoplasm, predominantly affecting adolescents and young adults. "By reviewing existing literature, we found another gene COLGALT2 which also initiated collagen glycosylation was up-regulated in metastatic osteosarcoma tissues than primary osteosarcoma tissues." (PMID 35842702, 2022). "Metastatic osteosarcoma is enriched in MSC-adipocytes and in vitro studies suggest that exosomes from ADMSCs increase proliferation and growth of osteosarcoma cells via the procollagen galactosyltransferase 2 (COLGALT2) pathway." (PMID 34283044, 2021). "COLGALT2 inhibition in MG63 cells suppressed the ADSC exosome-mediated fostering of osteosarcoma cell invasion, migration and proliferation in vitro." (PMID 32523950, 2020). "Then, in osteosarcoma cells, we evaluated COLGALT2, vimentin and matrix metalloproteinase 2/9 (MMP2/9) expression together with ADSC exosomes using qRT-PCR and western blotting." (PMID 32523950, 2020). "In this study, we compared COLGALT2 expression between primary and metastatic osteosarcoma tissues and found that metastatic tissues expressed significantly higher COLGALT2 levels." (PMID 32523950, 2020). "Our results showed that COLGALT2 was significantly upregulated in metastatic osteosarcoma tumors, which indicated a relationship between COLGALT2 expression and osteosarcoma progression." (PMID 32523950, 2020). "To understand the role of COLGALT2 in the osteosarcoma-promoting effect of ADSC exosomes, we first examined COLGALT2 and vimentin expression in exosome-treated osteosarcoma cells by immunofluorescence." (PMID 32523950, 2020). "According to these data, ADSC exosomes foster osteosarcoma progression by increasing COLGALT2 expression in osteosarcoma cells." (PMID 32523950, 2020). "In our research, we identified and isolated exosomes from ADSCs to assess the influence of COLGALT2 when ADSC osteosarcoma and exosomes were interacting." (PMID 32523950, 2020). "To characterize the role of COLGALT2 in the osteosarcoma-promoting effects of exosomes, we first tested COLGALT2 expression levels by qRT-PCR in two osteosarcoma cell lines." (PMID 32523950, 2020). "The evidence shows that COLGALT2, which is overexpressed in metastatic osteosarcoma tissues, has great impacts on the tumor-promoting effects of ADSC exosomes." (PMID 32523950, 2020). "Altogether, our results support that exosomes secreted by ADSCs in adipose tissues can activate the expression of COLGALT2 in osteosarcoma cells, which fosters cancer metastasis and growth by increasing vimentin and MMP expression." (PMID 32523950, 2020). "The aim of this study was to investigate the role of COLGALT2 in the osteosarcoma-fostering effects of ADSCs." (PMID 32523950, 2020). "Moreover, ADSC-EXOs facilitate osteosarcoma progression by increasing COLGALT2 expression in osteosarcoma cells." (PMID 36248361, 2022). "Additionally, we assessed the roles of ADSC exosomes and COLGALT2 in the osteosarcoma-promoting effects of ADSCs." (PMID 32523950, 2020). "We predicted that ADSC exosomes could increase COLGALT2 expression in osteosarcoma, which would promote osteosarcoma proliferation and osteosarcoma cell invasion." (PMID 32523950, 2020). "Thus, ADSC exosomes promoted osteosarcoma metastasis and growth, and these effects were counteracted by COLGALT2 inhibition." (PMID 32523950, 2020). "In this study, we focused on ADSC exosomes and demonstrated that they could induce COLGALT2 overexpression in osteosarcoma cell lines, which could increase osteosarcoma cell invasion, migration and proliferation in vivo and in vitro." (PMID 32523950, 2020). "In addition, higher expression of COLGALT2 was found to be associated with higher levels of vimentin and MMP2/9 in osteosarcoma cells." (PMID 32523950, 2020). "However, our knowledge regarding the exact mechanism of the actions of COLGALT2 that influence the progression and metastasis of osteosarcoma is limited." (PMID 32523950, 2020).
osteosarcoma (continued). "Although this finding still requires further investigation, we hypothesize that ADSC-secreted exosomes can induce COLGALT2 expression in osteosarcoma cells, accompanied by the downstream activation of vimentin and MMP2/9." (PMID 32523950, 2020). "To determine the possible mechanism that leads the ADSCs exosomes to increase COLGALT2 expression in osteosarcoma cells, we examined the mRNA level of COLGALT2 in ADSCs exosomes compared with MRC-5 cells exosomes, and higher COLGALT2 mRNA level was found in ADSCs exosomes." (PMID 32523950, 2020). "Our results showed that ADSC exosomes could foster the invasion, migration, and proliferation of osteosarcoma cells, together with increasing COLGALT2 expression." (PMID 32523950, 2020). "Our results also confirmed that COLGALT2 may mediate the osteosarcoma progression induced by ADSC exosomes." (PMID 32523950, 2020). "All the results suggest that COLGALT2 may mediate the osteosarcoma-promoting effects of ADSC exosomes." (PMID 32523950, 2020). "Because the expression of COLGALT2 may be related to tumor metastasis, we examined COLGALT2 expression in patients with osteosarcoma (using 12 paired primary and metastatic tumor tissues; all metastatic tumor tissues were from the lungs)." (PMID 32523950, 2020). "The procollagen galactosyltransferase 2 (COLGALT2) pathway is activated by ADSC-derived exosomes, leading to increased proliferation and development of osteosarcoma cells." (PMID 37289328, 2023). "Exosome treatment markedly increased COLGALT2, vimentin and MMP2/9 expression in the osteosarcoma cells." (PMID 32523950, 2020). "We constructed models of tibia osteosarcoma in nude mice and used human OS MG63 cells to determine how the osteosarcoma-promoting effects of ADSC exosomes are influenced by COLGALT2." (PMID 32523950, 2020). "We examined the potential roles of COLGALT2 in osteosarcoma and ADSC exosomes in communication between ADSCs and osteosarcoma cells." (PMID 32523950, 2020). "However, the two osteosarcoma cell lines expressed higher levels of COLGALT2 than the MRC5 cells; moreover, compared with that in U-2OS cells, COLGALT2 expression was remarkably greater in MG63 cells." (PMID 32523950, 2020). "Additionally, COLGALT2 inhibition attenuated metastasis and tumor growth, and ADSC exosomes promoted tumor progression, as demonstrated in a nude mouse model of osteosarcoma." (PMID 32523950, 2020). "However, at present, we have no knowledge of the role of COLGALT2 in the osteosarcoma-promoting effects of ADSCs." (PMID 32523950, 2020). "The inactivation of COLGALT1 in osteosarcoma cells led to collagen type I accumulation, and cells with inactive COLGALT1 and COLGALT2 genes could not be grown, suggesting that osteosarcoma cell viability and proliferation are impaired by a complete loss of collagen glycosylation." (PMID 32523950, 2020).
osteoarthritis (5 papers, 2023 to 2025). A noninflammatory degenerative joint disease occurring chiefly in older persons, characterized by degeneration of the articular cartilage, hypertrophy of bone at the margins and changes in the synovial membrane. "Potential novel associations included COLGALT2 and arthrosis (rs35937944, p.Tyr212Cys, P = 2 × 10−14), LGR5 and carcinoid syndrome (rs200138614, p.Cys712Phe, P = 4 × 10−9), and GREB1 and female infertility (rs755857714, p.Arg1339His, P = 4 × 10−9)." (PMID 39563277, 2024). "At this locus, harbouring the gene COLGALT2 and marked by osteoarthritis risk SNV rs11583641, 8 CpGs cluster within a 500-bp region of an intronic enhancer." (PMID 38430365, 2024). "Over 100 DNA variants have been associated with osteoarthritis (OA), including rs1046934, located within a linkage disequilibrium block encompassing part of COLGALT2 and TSEN15." (PMID 36538011, 2023). "LOF + MIS variants in ADAMTS6, SPRY2 and COLGALT2 are protective against osteoarthritis, whereas aggregation of these variants in ADAMTSL3, VIT, IL11 and THBS3 confer risk of osteoarthritis." (PMID 40205036, 2025). "The LOF + MIS burdens in COLGALT2 are protective against osteoarthritis." (PMID 40205036, 2025). "This functional fine-mapping approach has identified mechanistic links between mQTLs and further confirmed COLGALT2 [37–39TGFB1, RWDD2B and, most recently, WWP2 as osteoarthritis effector genes." (PMID 38430365, 2024).
breast carcinoma (1 paper, 2024). "Additionally, COLGALT2, a gene downregulated in breast cancer, showed a negative correlation with multiple bacterial species including C. morbi (rho = −0.528, p = 0.001) and T. medium (rho = −0.447, p = 0.008)." (PMID 38589501, 2024).
Hepatic steatosis (1 paper, 2022). Steatosis is a term used to denote lipid accumulation within hepatocytes. "Colgalt2 deficiency aggravates hepatic steatosis in mice on HFD." (PMID 35700043, 2022).
measles (1 paper, 2023). A highly contagious viral infection caused by the measles virus. "In measles, including six in whole blood (SOAT1, COLGALT2, AC021860.1, HCG11, METTL21B, and MRPL10), six in the lung tissue (GSTM4, PAQR6, RP11-617D20.1, SNX8, METTL21B, and ANKRD27), and two in the transformed fibroblast cells (CBWD2, and TSFM)." (PMID 37020999, 2023).
steatosis (1 paper, 2022). Increased lipid within the cytoplasm of cells. "Using real-time qRT-PCR assay, we further validated that both adropin and Colgalt2 were significantly upregulated in the liver, correlating with the reduction in steatosis and amelioration of NASH in MøFoxO1-KO mice." (PMID 35700043, 2022).
tumor (5 papers, 2019 to 2024). "EVs derived from adipose-derived stem cells (ADSCs) facilitate tumor proliferation and growth by regulating Wnt/β-catenin signaling, through the procollagen galactosyltransferase 2 (COLGALT2) pathway." (PMID 38598014, 2024). "ADSC exosome-treated tumor cells expressed higher levels of COLGALT2 and vimentin than control cells." (PMID 32523950, 2020). "Given our observation of the relationship between COLGALT2 and the tumor-promoting effects of ADSC exosomes, we next investigated whether COLGALT2 overexpression had tumor-promoting effects similar to those of ADSC exosomes." (PMID 32523950, 2020). "Furthermore, more Ki67 was found in the tumor tissues of the ADSC exosome group, which was accompanied by higher COLGALT2 expression levels." (PMID 32523950, 2020).
cancer (1 paper, 2020). A tumor composed of atypical neoplastic, often pleomorphic cells that invade other tissues. "Further studies should focus on the underlying mechanisms that mediate the immune regulation of COLGALT2 and facilitate cancer progression." (PMID 32523950, 2020). "Homosapien collagen beta (1-O) galactosyl transferase 2 (COLGALT2) is an important enzyme during collagen glycosylation, yet its biological functions in cancer are incompletely understood." (PMID 32523950, 2020).
COLGALT2 also shares sentences with these, for which no sentence is quoted: alcoholism (1 paper); carcinoid syndrome (1); colon cancers (1); female infertility (1); glioma (1); hepatotoxicity (1); inflammation (1); metastatic tumor (1); ovarian carcinoma (1); prostate carcinoma (1).